CD24 (CD24 molecule)
Diseases named in the same sentence as CD24 in open-access papers (continued):
Sharing a sentence is not in itself a finding about the gene and the disease.
breast cancer (continued). "Different subtypes and stages of breast cancer have their unique expression of stem cell markers such as CD44, CD24 and aldehyde dehydrogenase (ALDH) and the search for drugs which reduce cancer stemness is an essential investigation in drug discovery and development programs." (PMID 34208799, 2021). "Based on immunohistochemistry analysis of CD24 and CD44 expression in 50 breast cancer patients, Idowu MO also suggested that CD24-CD44+ BCSCs played a significant role in triple negative subtype of breast cancer." (PMID 34801088, 2021). "Excised xenografts were assessed histologically by H&E staining and immunohistochemistry for breast cancer marker (ERB1), proliferation marker (Ki67), mitotic marker (pHH3), hypoxia marker (HIF-2α), CSC markers (CD47, CD44, CD24, and CD133), and vascularization markers (CD31, CD34)." (PMID 34205080, 2021). "In breast cancer, CSCs were initially identified by low or negative expression of CD24 and high expression of CD4426." (PMID 34475402, 2021). "We sorted CD44+CD24−/low cells (BCSCs) and CD44+CD24+ cells (non-BCSCs) from MCF-7ADR breast cancer cells by fluorescence-activated cell sorting." (PMID 34403222, 2021). "In contrast, cells with low expression or absence of CD24 at the cell periphery were identified as CSCs in breast and prostate cancer and in circulating tumor cells in the blood of breast cancer patients." (PMID 34360932, 2021). "Liu and colleagues isolated CSCs (using ESA+/CD24−/CD44+/lin− CSC and ESA+/CD24+/CD44−/lin− non-CSC markers) from six breast cancer tissue samples and identified any changes in the miRNAs by miRNA microarray." (PMID 33916548, 2021). "In addition, we found HMGA2 knockdown increased CD24+ CD44+ breast cancer in moderate HMGA2 expressed cell line and increased CD24+ CD44- in HMGA2 overexpressed cell lines." (PMID 34680349, 2021). "Because breast CSCs are crucial for the metastasis of breast cancer, whether CD44-/CD24- cells could convert into CSCs was tested in vitro and in vivo." (PMID 34318746, 2021). "Moreover, both Ber and C60-Ber nanocomplex treatment significantly decreased expression of adaptor protein Ruk/CIN85, which was found to modulate CD44 and CD24 expression levels and to be involved in the maintenance of CSC features in breast cancer cells." (PMID 34683705, 2021). "(A) Immunofluorescent analysis of the percentages of CD44-/CD24- cells in tissue samples from breast cancer patients with or without tumor metastasis." (PMID 34318746, 2021). "A possible role of miRNAs in the determination of breast cancer stem cells has been suggested through the demonstration of differential expression of miRNAs in CD44+/CD24-/low breast cancer stem cells versus non-tumorigenic cancer cells." (PMID 34804971, 2021). "Given that CSCs are crucial for breast cancer progression and metastasis, RHBDL2 may be a new therapeutic target for control of CD44-/CD24- cell conversion into CSCs to reduce CSC pool size and limit breast cancer progression and metastasis." (PMID 34318746, 2021). "Originally identified as self-renewing cells in leukemia with a CD34+CD38- phenotype, they have since been identified in several solid and hematologic malignancies, including breast cancer, as both hyperproliferative and slow-cycling cells with a consensus CD44+CD24-/ALDH1+ phenotype." (PMID 35582030, 2021). "Recent studies have shown that CD24 correlates with poor prognosis in many types of tumor tissues, including gliomas, hepatocellular carcinoma (HCC), and breast cancer." (PMID 32394616, 2020). "We isolated the compound 6-methoxymellein, which inhibits the proliferation and migration of breast cancer cells, reduces mammosphere growth, decreases the proportion of CD44+/CD24− cells in breast cancer cells and decreases the expression of stemness-associated proteins c-Myc, Sox-2 and Oct4." (PMID 32977636, 2020).
breast cancer (continued). "Approaches with the knockdown of GRP78 helped to elucidate that this chaperone is required for the self-renewal ability and radioresistance in CSC-like cell fractions from breast cancer MCF-7 cells and also for chemo- and radioresistance in CD24(−)/CD44(+) stem cells of head and neck cancer." (PMID 32268506, 2020). "CD24 and ALDH1 are widely used CSC markers in breast cancer." (PMID 32909943, 2020). "In breast cancer, different subsets of CSCs were identified based on ALDH1, CD44, and CD24; and the two subpopulations (epithelial-like ALDH1+, mesenchymal like CD44+/CD24–) were shown to be capable of inter converting among themselves as well as give rise to non-CSCs." (PMID 32426371, 2020). "Specifically, in luminal breast cancers, which constitute 70% of all breast cancers, it is critical to assess the tumorigenicity and BCSC-like properties of CD44low/CD24–/low/ALDH– cells, because this subpopulation reflects the major luminal breast cancer phenotype." (PMID 32423137, 2020). "In a similar model with breast cancer, HSP27 was found to be responsible for vasculogenic mimicry activity in populations of mammosphere-forming CD24(−)CD44(+)ALDH(+) CSCs; the activity’s manifestation was mediated by the EGF-triggered signaling pathway, resulting in HSP27 phosphorylation." (PMID 32268506, 2020). "In addition, many prognostic markers of BRCA have been reported: CD24, EGFR, CXCR 4 genes can predict the metastasis and prognosis of breast cancer." (PMID 33365308, 2020). "Of note, the breast CSCs enriched from the breast cancer cell lines have been previously shown to contain functional cancer stem cells with high CD44 and low CD24 expression and retain high tumorigenic activity when injected into the mammary fat pad of SCID mice." (PMID 32260399, 2020). "In general, SCLC CTC spheroids are not sensitized to salinomycin and the difference in chemosensitivity between single cells and aggregates is far lower than the 100fold disparity observed in breast cancer mammospheres and tumor cells exhibiting a CD44+/CD24− CSC phenotype." (PMID 31446534, 2020). "Furthermore, the report found that loss of EphA5 resulted in higher expression of cancer stem cell (CSC) markers in HER2-positive breast cancer cells, including CD44+/CD24-/low, NANOG, CD133+." (PMID 31956298, 2020). "In addition, CD24, CD44, CD133, EpCAM, and ALDH1 have been documented as beneficial CSC markers in the chemically-induced rat mammary carcinoma model." (PMID 33375383, 2020). "Mammosphere assay, FACS analysis for CD24-/CD44+ population and/or serial dilution xenograft mouse model might be performed to confirm the effect of metformin on stemness in breast cancer cells." (PMID 30625181, 2019). "The breast cancer cell lines we used to conduct our experiments—namely, MCF-7 and MDA-MB-468—contained a functional CD44+CD24-/low cancer stem cell subpopulation, as per the published literature and our own preliminary experiments had indicated (data not shown)." (PMID 31627418, 2019). "CD24 is absent in normal T cells or monocytes, however it is present in the cells of cancers, including gliomas, breast cancers, hepatocellular carcinomas (HCCs), esophageal squamous cell carcinomas, and CRCs." (PMID 31614769, 2019). "Breast Cancer Stem Cells (BCSCs) were initially described in 2003 by Al-Hajj and colleagues, who found that the CD44+CD24−/lowLin− fraction was significantly enriched for cells with tumor forming ability as compared to the CD44+CD24+Lin− population." (PMID 31619007, 2019). "Intriguingly, dormant MDA-MB-231 cell did not belong to the CD44HIGH/CD24-/LOW breast cancer stem cell population." (PMID 31239543, 2019). "While exposing these mesenchyme-like breast cancer cells to GSK3β inhibitors increased CD24 expression, we did not see any change in the CD44 expression." (PMID 30845991, 2019). "We have shown previously that a distinct CD44+/CD24- sub-population of breast cancer CTCs is not detectable by CellSearch® (“stem-like” CTCs)." (PMID 31003475, 2019).
breast cancer (continued). "The study of CD44/CD24 and ALDH1 expression could be the most appropriate to identify BCSCs with distinct levels of differentiation from breast cancer populations." (PMID 31505803, 2019). "CD24, proposed as a β-catenin target in CRC cells, is expressed in breast cancer cells." (PMID 31614769, 2019). "Breast cancer was the first human solid tumor proven to consist of heterogeneous populations of cells: non-CSCs and CSCs; specifically the CSCs subpopulation (CD44+ CD24−/low) is capable of initiating tumor growth in immune-deficient mice." (PMID 30728463, 2019). "By contrast, forced CD24 expression in breast cancer cells with low or no CD24 expression (CD24−) reduces cell proliferation." (PMID 31614769, 2019). "Conversely, even 100 times more of CD44−/CD24+ breast cancer cells injected to NOD/SCID mice failed to form tumors." (PMID 30200262, 2018). "To follow up on our findings of epithelial-like and mesenchymal-like breast cancer stem cells, we isolated three cellular populations from reduction mammoplasty samples (n = 3 independent biological replicates) by flow cytometry: ALDH+, CD44+, and CD24+." (PMID 29606612, 2018). "But it also has been shown that ERα-positive breast cancer cells can secrete FGFR and EGFR ligands in response to estrogen, which can act as paracrine mediators to promote CSC activity and expand the fraction of CD44+ CD24−/lo cells." (PMID 29600163, 2018). "Furthermore, although CD44+/CD24-/low and ALDH1 were suggested as potential markers for breast cancer stem cells, their clinicopathologic and prognostic significance remains controversial." (PMID 29416796, 2018). "The presence of CD44 promotes tumorigenesis and metastasis in breast cancer, as does the absence of CD24." (PMID 30542507, 2018). "CD44 and CD24 expression was evaluated by double-staining immunohistochemistry technique in 165 cases of breast cancer tissues, and the cancer cell with CD44+/CD24-/low phenotype might be considered as BT-IC." (PMID 29423076, 2018). "Our result indicating that only very few patients showed potential breast cancer stem cell markers, CD44+/CD24- (one out of 99 patients) or ALDH1 (four out of 99 patients) may be in accordance with previous studies of proof of concept on cancer stem cells." (PMID 29416796, 2018). "However, it is still unclear how the STAT3 pathway regulates the growth of CD44+/CD24– and ALDH1 positive breast cancer cells in TNBC tumor models." (PMID 30542507, 2018). "Because breast cancer invasiveness is functionally linked to loss or reduction of the CD24 epithelial surface marker and development of an invasive basal-like phenotype, we assessed CD24 expression in breast cancer cells under nonadherent conditions." (PMID 30180881, 2018). "CD24−/CD44+ cells and ALDH1+cells are widely considered to be breast cancer stem cells." (PMID 30482232, 2018). "Although we have demonstrated the correlation between CD44/CD24 ratio, ALDH1+ and the development, metastasis of breast cancer, whether these CSC markers are conserved and how they are dynamically changed during tumor progression have yet to be elucidated." (PMID 29062075, 2017). "Additionally, growing evidence suggests that breast cancer cells that do successfully metastasize have a stem-like phenotype including high activity of aldehyde dehydrogenase (ALDH) and/or a CD44+CD24- phenotype." (PMID 28498874, 2017). "The combination of high CD44/CD24 ratio and ALDH1+ may be a more accurate and reliable way to refine the definition of CSCs in breast cancer." (PMID 29062075, 2017). "In accordance to this observation, TRIM28 reduction did not change the percentage of CSCs characterized by the CD44+CD24−/low phenotype in vitro in the tested breast cancer cell lines." (PMID 27845900, 2017).
breast cancer (continued). "Controversially, in vivo xenograft analyses of breast cancer cell lines were unable to demonstrate ALDH+ or CD44+/CD24- CSC localization patterns, or demonstrate a correlation between the frequency of CD44+/CD24- CSCs and tumor metastasis as observed in patients with breast cancer." (PMID 29348905, 2017). "CD44+CD24- CSCs were observed in 77.8% (28/36) of luminal breast cancers while the number of these cells was not related on the luminal subtype: A, B HER2-, and B HER2+ (data not shown)." (PMID 28977854, 2017). "In exosomes-derived from breast cancer patient serum, only CD24 was detectable, but EpCAM was absent due to metalloproteinase-dependent cleavage." (PMID 28085080, 2017). "This trend was more similar to that with the expression level of ALDH1 compared to CD44/CD24 in the cell lines, indicating that the expression level of ALDH1, rather than CD44/CD24, is positively correlated with the metastatic capacity of breast cancer." (PMID 29062075, 2017). "The EpCAM+, CD24−, CD44+, and ALDH+ populations across different subtypes of breast cancers represent anatomically distinct BCSCs with respective EMT (epithelial-to-mesenchymal transition) and MET (mesenchymal-to-epithelial transition) gene expression profiles." (PMID 29258583, 2017). "To test this hypothesis, we investigated the role of CD44/CD24 ratio and ALDH1+ in the proliferation, tumorigenesis, migration and metastasis of breast cancer." (PMID 29062075, 2017). "CD44/CD24 and ALDH1 are widely used cancer stem cell (CSC) markers in breast cancer." (PMID 29062075, 2017). "As CD44high/CD24-/low and/or ALDH1 have been commonly used in the characterization of breast CSCs,16, 19, 20, 21 these results suggest that some factors produced by breast cancer cells themselves (i.e., autocrine factors) after drug withdrawal facilitate CSC enrichment." (PMID 28703802, 2017). "Indeed, the examined breast cancer cell lines are characterized by different proportion of CD44 and CD24 expressing cells." (PMID 27845900, 2017). "In the present study, we systematically investigated the expression of CD44, CD24 and ALDH1 in different subtypes of breast cancer cell lines, and explored their possible roles during cancer progression both at the cellular level and in the xenotransplanted mice model." (PMID 29062075, 2017). "The CD44/CD24 ratio and ALDH1 level were stable in the primary tumor and the distant metastases, and existed in CTCs, indicating the conservation of these two stem markers during the progression and metastasis of breast cancer." (PMID 29062075, 2017). "Although these studies were not performed in breast cancer cells, immunohistochemical expression of CD24 in early primary invasive breast cancers has been significantly associated with poor prognosis." (PMID 27706047, 2016). "Studying tumorigenic cells separated in vitro, from malignant human breast cancer-derived pleural effusions, Al Hajj and colleagues isolated a cell population characterized by high CD44 expression and low or undetectable levels of CD24 (CD44+/CD24−/low)." (PMID 26757880, 2016). "With respect to these markers, thyroid cancers are similar to other malignancies in terms of expression of CD44+CD24−, ALDH+, and CD133+ (breast cancers), CD133+ and ALDH+ (colon cancers), and CD44highESAlow-EMT and CD44highESAhigh-EMT in oral squamous cell carcinomas (see Ref." (PMID 26973599, 2016). "The MCF7/C6 cells with gained radiation resistance after a long term treatment with fractionated ionizing radiation were derived from human breast cancer MCF7 cell line, and are enriched with cells expressing putative breast cancer stem cell biomarker CD44+/CD24-/low/ALDH+." (PMID 27036550, 2016). "In B cells and breast cancer cells CD24 excludes CXCR4, the receptor for Stromal Cell Derived Factor-1 (SDF-1), from lipid rafts whereas in the absence of CD24, CXCR4 can enter." (PMID 28083532, 2016).
breast cancer (continued). "Finally, we demonstrate that increased expression of CD24 correlated with a worse DFS in both TNBC and HR+ breast cancers." (PMID 28721382, 2016). "Therefore, we first determined the effect of CCL2 gene silencing on the numbers of CD24-/CD44+ cells, a well characterized breast cancer stem cell population." (PMID 27283985, 2016). "Phenotypically, breast cancer stem-like cells (BCSCs) express high CD44 (cell-surface glycoprotein CD44) and low CD24 (cell-surface glycoprotein CD24) (CD44high/CD24low) and also have increased ALDH1 (aldehyde dehydrogenase 1) activity (identified by ALDEFLUORTM assay, StemCell Technologies)." (PMID 26821054, 2016). "We correlated the SAGE database expression patterns with our list of neurogenes to identify neurogenes that are differentially expressed in breast cancer tissue compared with healthy epithelium and that are differentially expressed in each cell subtype (CD44+ vs. CD24+)." (PMID 26673618, 2016). "While CD24 expression inversely correlated with tumor grade, and thus generally decreased in progressive mammary tumors, it remained robustly expressed in some but not all more advanced prostate tumors." (PMID 26978528, 2016). "To characterize the role of neurotransmitters, neuropeptides, neurotrophic factors, and axonal guidance molecules in breast cancer progression, we analyzed the expression of several neurogenes in breast cancer patients and in CD44 and CD24 expression databases." (PMID 26673618, 2016). "It is well known that negative expression of CD24 has been characterized as one of the biomarkers of breast cancer stem cells, resulting in functional promotion of breast tumor initiation and progression." (PMID 26830684, 2016). "Cells expressing the biomarkers of breast cancer stem cells (BCSCs; e,g., CD44+/CD24-/low/ALDH+) were further sorted and confirmed in one of these clones (MCF7/C6), indicating that BCSCs can survive long-term fractionated radiation and be responsible tumor repopulation with radiation resistance." (PMID 27036550, 2016). "CD24 was initially identified as a negative marker for CSCs in breast cancer, but has more recently been described as a positive CSC marker in lung cancer, colorectal cancer, and triple-negative breast cancer." (PMID 26981578, 2016). "Interestingly, a recent study illustrated that CD24 expression can be induced by HER2 overexpression, and silencing of CD24 downregulated HER2 expression in breast cancer cells." (PMID 26444008, 2015). "For example, CD24 is frequently used to isolate CSCs from solid tumours, e.g. breast cancer, but does not enrich tumour-initiating cells from UC." (PMID 26606927, 2015). "Importantly, specific downregulation of PD-L1 in claudin-low breast cancer cells showed signs of EMT reversal as manifested by CD44 and Vimentin downregulation and CD24 upregulation." (PMID 26245467, 2015). "Although several studies suggest that it is the lack of CD24 expression that characterizes breast cancer stem cells, it is known that cell-surface markers are not conserved among different tumors, due to differences in the driver mutations." (PMID 26040280, 2015). "Concerning the expression of CD24 in the four molecular subtypes determined on the basis of immunohistochemical staining for ER, PR, and HER2, CD24 expression varied according to breast cancer subtype (P = 0.041); the HER2 subtype had the highest proportion of CD24-high tumours (39.0%)." (PMID 26444008, 2015). "CD24 and CD44 surface staining was used to estimate the CSC population of breast cancer cells." (PMID 26522589, 2015). "Although CD24 knockdown had no in vitro effect on the cells, we next determined its role in mammary tumor growth in vivo." (PMID 26040280, 2015). "A number of potential markers of breast cancer stem cells have been identified (CD44+CD24−, ALDH1+), but these do not universally mark breast cancer stem cells, with variation evident between individual tumors." (PMID 25849559, 2015).